FAS (Fas cell surface death receptor)
Diseases named in the same sentence as FAS in open-access papers (continued):
Sharing a sentence is not in itself a finding about the gene and the disease.
Hodgkins lymphoma (2 papers, 2012 to 2025). A heterogeneous group of malignant lymphoid neoplasms of B-cell origin characterized histologically by the presence of Hodgkin and Reed-Sternberg (HRS) cells in the vast majority of cases. "It is already known that individuals with heterozygous germline FAS variants have high risk for both non-Hodgkin and Hodgkin lymphomas, with incidences 14 and 51 times greater than the general population, respectively." (PMID 40755914, 2025).
Hypercholesterolemia (2 papers, 2014 to 2024). An increased concentration of cholesterol in the blood. "Rosuvastatin treatment demonstrated amelioration of hypercholesterolemia induced by a high-fructose diet, effectively reducing TC even in the presence of allergic asthma (FS: 74.0 ± 6.9 mg/dL vs. F: 137.7 ± 9.2 mg/dL, p < 0.0001; FAS: 87.4 ± 6.1 mg/dL vs. FA: 118.6 ± 9.3 mg/dL, p < 0.0001." (PMID 39683498, 2024).
Infertility (2 papers, 2019 to 2025). "FAS is reduced in women who are conflicting from recurrent pregnancy loss and unexplained infertility which results in the downregulation of apoptotic signaling in the epithelial cells during embryo implantation." (PMID 41417751, 2025). "In fact, these results confirm that FAS-670 A/G polymorphism is a risk factor predisposing the male sex to infertility in the Turkish population." (PMID 31195645, 2019). "Only one study demonstrates a significant association between infertility inpatients and FAS-670A/G polymorphism (p-value < 0.05)." (PMID 31195645, 2019). "According to review of the literature, down-regulation of FAS expression and/or up-regulation of FASL expression have been indicated in many types of disorders and diseases such as infertility." (PMID 31195645, 2019).
Intellectual disability (2 papers, 2009 to 2021). "We also characterized baseline retinal phenotypes of mice with homozygous knock-in of a GOF FAS variant associated with human intellectual disability and impaired adult neurogenesis." (PMID 34425110, 2021).
keloid (2 papers, 2022). An irregularly shaped, elevated mark on the skin caused by deposits of excessive amounts of collagen during wound healing. "Since the FAS gene was understood to be one of the candidate genes causing keloids for this pedigree, four markers besides all the known genes relating to apoptosis or tumorigenesis in the 10 Mbp region around the FAS gene on chromosomes 10q23.31 were identified as microsatellite markers." (PMID 36483731, 2022).
laryngeal carcinoma (2 papers, 2020 to 2021). Carcinoma that arises from the laryngeal epithelium. "Two of them (VEGFA rs13207351 and FAS rs2234768) were associated with overall survival for patients with laryngeal cancer and NPC, respectively, with VEGFA rs13207351 showing the most promise for its prognostic value in the subgroup of laryngeal cancer patients." (PMID 33800431, 2021).
liver dysfunction (2 papers, 2013 to 2022). "Our study shows up-regulation of SREBP-1c and FAS in the 4 M adult FD offspring, which may play a pathologic role in the predisposition to liver dysfunction." (PMID 35055185, 2022).
lymphedema (2 papers, 2021 to 2023). Excess fluid collection in tissues, causing swelling. "We also analysed the degree of differentiation at the mRNA expression levels of typical adipogenic markers (PPARγ, perilipin, FAS, DGAT2, ATGL) -but we could not find major differences between cells derived from lymphedema patients and control subjects." (PMID 33854130, 2021).
male infertility (2 papers, 2019 to 2025). The inability of the male to effect fertilization of an ovum after a specified period of unprotected intercourse. "The aim of this study was to investigate the gene polymorphisms FASL-844C/T and FAS-670A/G in the promoter region to evaluate susceptibility to male infertility." (PMID 40531769, 2025). "The current study aimed to investigate the gene polymorphisms FASL-844C/T and FAS-670A/G in the promoter region to evaluate susceptibility to male infertility." (PMID 40531769, 2025). "Background and Objectives: Studies suggest that FAS/FASL polymorphisms are associated with male infertility; however, their results are still inconclusive." (PMID 31195645, 2019). "For precise determination of FAS/FASL polymorphisms effects on male infertility, large-scale case-control studies should be performed." (PMID 31195645, 2019). "We believe that since the number of our included studies was small, the results from the correlation of FAS-670A/G polymorphism and male infertility should be interpreted with caution." (PMID 31195645, 2019). "FAS homozygous mutant genotype (GG) and FASL homozygous mutant genotype (TT) acted as risk factors for male infertility." (PMID 40531769, 2025). "Several studies have reported an association between the polymorphisms of FAS-670A/G and FASL-844C/T and male infertility risk." (PMID 31195645, 2019). "For the first time in the present meta-analysis, we studied the genetic relevance between FAS-670A/G and FASL-844C/T polymorphisms of different models and the risk of male infertility." (PMID 31195645, 2019). "For performing the meta-analysis, pooled odds ratio (OR) values with 95% confidence interval (CI) was applied in order to analyze the strength of association between the FAS/FASL polymorphisms and risk of male infertility." (PMID 31195645, 2019). "The present study, on the other hand, is the first meta-analysis to examine and study the possible association of FAS-670A/G polymorphism with male infertility; the results proved this variation to not affect male fertility." (PMID 31195645, 2019). "Therefore, this study evaluated the association between the polymorphisms of FAS-670A/G and FASL-844C/T with male infertility by performing a systematic review and meta-analysis based on available independent studies." (PMID 31195645, 2019). "Therefore, this systematic review and meta-analysis aimed to summarize and clarify the overall association of FAS/FASL polymorphisms and risk of male infertility." (PMID 31195645, 2019). "FAS homozygous mutant genotype (GG) and FASL homozygous mutant genotype (TT) act as etiologic factors in male infertility." (PMID 40531769, 2025). "Since different studies have reported the importance of FAS and FASL genes in spermatogenesis, it is plausible that polymorphisms of these genes could have a potential influence on the expression of FAS and/or FASL and, therefore, might be related to male infertility." (PMID 31195645, 2019).
marginal zone lymphoma (2 papers, 2020 to 2022). A usually indolent mature B-cell lymphoma, arising from the marginal zone of lymphoid tissues. "Splice site mutations of the FAS gene affecting its functionally relevant death domain are rather specific for PCMZL, being detected in >60% of investigated cases and only rarely in other subtypes of marginal zone lymphoma." (PMID 36358692, 2022). "In addition, for cases with single BCL6-trans signature, the mutations in several genes were also frequently determined in marginal zone lymphoma, including NOTCH2 (14.6%, 6/41), KLF2 (34.1%, 14/41), TNFAIP3 (19.5%, 8/41), and FAS (17.1%, 7/41) mutations." (PMID 32736575, 2020).
meningioma (2 papers, 2014 to 2019). A generally slow growing tumor attached to the dura mater. "Elisa analysis demonstrated that rapamycin upregulated FAS expression in a dose‐dependent manner in primary pituitary adenoma and meningioma cells of PAM." (PMID 31665029, 2019). "Following treatment with 10 nM rapamycin in primary meningioma cells, the rate of apoptosis (P = 0.003) and the level of FAS (P = 0.0006) significantly increased compared with the control." (PMID 31665029, 2019).
metastasis (2 papers, 2017 to 2021). The spread or migration of cancer cells from one part of the body (where they first appeared) to another. "STAMBPL1-FAS fusion isoform was identified in sample 1 M (metastasis cancer) and 2 M (the metastasis cancer): XM_011539985 from STAMBPL1 and XM_011539766.2 from FAS." (PMID 33907296, 2021).
metastatic colorectal cancer (2 papers, 2024 to 2025). "SUV39H1 deposits H3K9me3 at the promoter of the cell death receptor–encoding FAS gene, repressing expression and inhibiting apoptosis in metastatic colorectal cancer cells." (PMID 40059829, 2025). "An example of a direct mode of H3K9me3 action is the silencing of Fas (Fas cell surface death receptor) in metastatic colorectal cancer (CRC)." (PMID 39519018, 2024).
microcephaly (2 papers, 2016 to 2022). A congenital or acquired developmental disorder in which the circumference of the head is smaller than normal for the person's age and sex. "In fatal cases of ZIKV-induced microcephaly, FAS, FASL, and tumour necrosis factor (TNF)-α were also overexpressed and directly regulated the mechanisms of neural parenchymal cell injury." (PMID 35746675, 2022).
myocarditis (2 papers, 2019 to 2022). Myocarditis is a condition that is characterized by inflammation of the heart muscle (myocardium). "miR-98 can affect the pathogenesis of myocarditis by binding to FAS/FASL gene targets." (PMID 36193199, 2022).
oral cancer (2 papers, 2017 to 2023). "The results from the mouse oral cancer cells were consistent with those from human HNC cells showing a significant increase in MARCHF8 protein levels and a decrease in FAS, TRAIL-R1, and TRAIL-R2 protein levels in mEERL cells compared to NiMOE cells." (PMID 36867660, 2023). "Suberoylanilide hydroxamic acid (SAHA) markedly enhanced the expressions of DR4, DR5, Fas cell surface death receptor (Fas), and the Fas ligand (FasL; FASLG) in oral cancer Ca9-22 and SAS cells." (PMID 28708091, 2017).
osteoarthritis (2 papers, 2023 to 2024). A noninflammatory degenerative joint disease occurring chiefly in older persons, characterized by degeneration of the articular cartilage, hypertrophy of bone at the margins and changes in the synovial membrane. "For the 8 gene loci ESR1 rs2234693, CYP19A1 rs700518, ADAM12 rs3740199, ACE I/D rs4340, VDRrs731236, TGF-β rs1982073, FAS rs1800682, ADAMTS5 rs226794, the cumulative sample sizes were deemed sufficient to conclude that they are not correlated with osteoarthritis." (PMID 39248710, 2024).
rheumatic disease (2 papers, 2013 to 2020). "They revealed an association between rheumatic diseases and the FAS A-670G polymorphism in the dominant model." (PMID 24348139, 2013). "Moreover, they indicated an association between the FAS-670 G allele carrier and rheumatic diseases in the Asian." (PMID 24348139, 2013). "One previous meta-analysis including SLE, RA, SSc, pSS, JIA, and SPA demonstrated that the FAS −670 A/G polymorphism might be associated with the risk of rheumatic disease, especially in Asians, SLE and RA, and the FAS −1377 G/A polymorphism was associated with SLE risk." (PMID 31840751, 2020).
Salmonella Infections (2 papers, 2019 to 2023). Infections with bacteria of the genus SALMONELLA. "Our results showed that the expression of FAS in HD11 cells was down-regulated following salmonella infection, indicating that apoptosis of macrophages may be impaired." (PMID 31703342, 2019). "Interestingly, our SILAC results revealed that several members of the Rho GTPases network (CDC42, FAS, and MYC) underwent dynamic acetylation following Salmonella infection." (PMID 36812247, 2023).
systemic sclerosis (2 papers, 2023 to 2024). A chronic disorder, possibly autoimmune, marked by excessive production of collagen which results in hardening and thickening of body tissues. "A previous study showed that FAS on mouse BM-MSCs could recruit activated T cells through MCP-1 secretion regulation and subsequently induce immune tolerance in systemic sclerosis and experimental colitis in mice." (PMID 37957770, 2023).
adenoma (1 paper, 2007). A neoplasm arising from the epithelium. "In addition, FAS expression was significantly upregulated in mouse xenografts in Caco-2 intermediate adenoma cells and downregulated for in the HT29 carcinoma cells." (PMID 17551494, 2007).
alcohol abuse (1 paper, 2021). The use of alcoholic beverages to excess, either on individual occasions ("binge drinking") or as a regular practice. "More specifically, alcohol abuse was more frequent in patients with homozygous T FAS rs2234768 (−690) compared to those with heterozygous CT (81% vs. 59.3%)." (PMID 33800431, 2021). "Among non-NPC patients, FAS rs2234768 (−690) was significantly associated with alcohol abuse (Fisher’s p = 0.033)." (PMID 33800431, 2021).
alveolar rhabdomyosarcoma (1 paper, 2019). A rapidly growing malignant mesenchymal neoplasm. "A prior study documented resistance to FAS-mediated cell death in alveolar rhabdomyosarcoma cell lines and proposed that targeting the FAS-pathway may lead to treatments for rhabdomyosarcoma with gene fusion." (PMID 31480361, 2019).
atrophic gastritis (1 paper, 2011). "These polymorphisms were also associated with the risk of atrophic gastritis, however the data published on the association with risk for GC are still scarce and there are no reports on the role FAS/FASL polymorphisms with respect to GC in Caucasians." (PMID 21864388, 2011).
Atrophy (1 paper, 2017). Any weakening or degeneration, especially through lack of use. "FAS was indicated to be associated with the severity of atrophy in CD." (PMID 29379596, 2017).
brain injury (1 paper, 2023). Acute and chronic (see also brain INJURIES, CHRONIC) injuries to the brain, including the cerebral hemispheres, CEREBELLUM, and brain STEM. "Brain injury results in an increase in dsDNA in the blood, causing AIM2 inflammasome activation in blood monocytes and IL-1β release, which subsequently induces FAS ligand (FASL)-FAS-dependent T cell apoptosis leading to immunosuppression." (PMID 37216118, 2023).
brucellosis (1 paper, 2024). Brucellosis is a bacterial infection that spreads from animals to people via unpasteurized dairy products or by exposure to contaminated animal products or infected animals. "The upregulated genes in granzyme/perforin, TNF, XAF1 and FAS apoptosis pathways may result in elevated apoptosis of CD8+ T cells in brucellosis patients and thus directly inhibit CD8+ T‐cell‐mediated responses." (PMID 39135683, 2024). "Further analysis found that granzyme/perforin, TNF, XAF1, and FAS apoptosis pathways might contribute to apoptosis of NK cells in patients with brucellosis, potentially exerting a direct inhibitory effect on NK cell‐mediated responses." (PMID 39135683, 2024).
cataract (1 paper, 2015). Partial or complete opacity of the crystalline lens of one or both eyes that decreases visual acuity and eventually results in blindness. "CCL2, DUSP1, FAS and transcription factor c-Jun may be used as specific therapeutic molecular targets in order to treat cataracts induced by GCs." (PMID 25672806, 2015).
Chlamydia infection (1 paper, 2015). "Chlamydia infection is known to interfere with apoptosis signaling induced by various stimuli like staurosporine, etoposide, TNF-α, FAS antibody and granzyme B/perforin." (PMID 25906164, 2015).
common variable immunodeficiency (1 paper, 2022). "Finally, ALPS or ALPS-like features may also arise from the complementary effect of variants in CASP10 and in another non-FAS gene, such as CASP8 or TNFRSF13C (i.e., BAFF receptor, whose mutations are typically associated with common variable immunodeficiency, CVID)." (PMID 35059842, 2022).
cryptococcal infection (1 paper, 2025). "A heterozygous FAS mutation (p.S19L) was identified by WES in one of our patients; however, its association with cryptococcal infection remains unclear." (PMID 41245252, 2025).
cutaneous T cell lymphoma (1 paper, 2020).
deafness (1 paper, 2018). An inherited or acquired condition characterized by the complete loss of the ability to hear from one or both ears. "Interestingly, mutations in the CDH23 gene of the cell adhesion domain result in deafness and hearing loss is closely associated with FAS." (PMID 29997484, 2018).
edema (1 paper, 2024). An abnormal accumulation of fluid beneath the skin, or in one or more cavities of the body. "A substantial increase in apoptosis or apoptotic biomarkers (e.g. TNF, FAS, Bax, Bad, FAS/FASL and caspases-3/8) was commonly observed in leukocytes, alveolar cells and endothelial cells of lung tissue from severe P. falciparum malaria patients with pulmonary edema and experimental MA-ALI mice." (PMID 38303078, 2024).
embryonal carcinoma (1 paper, 2021). A non-seminomatous malignant germ cell tumor characterized by the presence of large germ cells with abundant cytoplasm resembling epithelial cells, geographic necrosis, high mitotic activity, and pseudoglandular and pseudopapillary structures formation. "Ectopic FAS expression at the tumor site was recently shown to improve CAR T cell efficacy against embryonal carcinomas by enabling antigen-independent FASL-dependent tumor cell lysis." (PMID 34771652, 2021).
endometrial adenocarcinoma (1 paper, 2022). "In contrast, mifepristone could inhibit cell growth and induce apoptosis in Ishikawa endometrial adenocarcinoma cells through caspase-3 activation and regulating apoptotic genes such as BCL2/BAX and FAS/FASLG." (PMID 35869506, 2022).
gallbladder cancer (1 paper, 2014). "Hence, the present study aimed to investigate the association of functional SNPs of DR4 (rs20575, rs20576 and rs6557634), FAS (rs2234767) and FASL (rs763110) with gallbladder cancer (GBC) risk." (PMID 24587306, 2014).
gallstones (1 paper, 2014). Solid crystalline precipitates in the biliary tract, usually formed in the gallbladder, resulting in the condition of cholelithiasis. "Since GBC is often associated with gallstones, we stratified patients on the basis of presence/absence of gallstone to see the combined effect of gallstone and DR4, FAS and FASL variants on GBC risk." (PMID 24587306, 2014).
goiter (1 paper, 2021). Enlargement of the thyroid gland usually caused by lack of iodine in the diet, hyperthyroidism, or thyroid nodules. "A rat model of goiter showed that the elevation of FAS protein expression was associated with an increased number of apoptotic cells." (PMID 34880333, 2021).
HCMV infection (1 paper, 2021). "HCMV infection suppressed the cell surface expression of FAS and, consequently, protected infected cells against FAS-mediated apoptosis." (PMID 33921122, 2021).
heart failure (1 paper, 2025). Inability of the heart to pump blood at an adequate rate to meet tissue metabolic requirements. "The in vivo experiments also showed that the cardiomyocytes-specific overexpression of CPNE5 can improve cardiac dysfunction in a mouse heart failure model and inhibit cardiomyocyte apoptosis by reducing the expression of FAS protein." (PMID 40894904, 2025). "Taken together, our findings provide evidence for strategies to interfere with FAS localization to the cell membrane during the early secretory phase, which could serve as molecular targets for the treatment of heart failure." (PMID 40894904, 2025).
leiomyosarcoma (1 paper, 2021). An uncommon, aggressive malignant smooth muscle neoplasm, usually occurring in post-menopausal women. "HDAC9 can influence H3K27 acetylation in leiomyosarcoma and enhance cell survival by repressing Fas cell surface death receptor (FAS) transcription." (PMID 35008848, 2021).